RNF40 (ring finger protein 40)
Diseases named in the same sentence as RNF40 in open-access papers (continued):
Sharing a sentence is not in itself a finding about the gene and the disease.
cancer (19 papers, 2017 to 2025). A tumor composed of atypical neoplastic, often pleomorphic cells that invade other tissues. "Monoubiquitination of histone 2B (H2Bub1) by the heterodimeric ubiquitin ligase complex RNF20/RNF40 has been described to have tumor suppressor functions and loss of H2Bub1 has been associated with cancer progression." (PMID 33070155, 2020). "RNF20 and RNF40, which are implicated as tumor suppressor genes, are mutated or misregulated in various types of cancers." (PMID 29058668, 2017). "The human homologs of yeast BRE1, RNF20 and RNF40 are mutated and misregulated in different types of cancers." (PMID 29058668, 2017). "In another apparent contrast, loss of RNF20 has been linked with an inflammatory phenotype in colorectal cancer, while loss of RNF40 would appear to have a protective effect against the development of an inflammatory phenotype in the same cancer, both involving NF-κB signalling." (PMID 30669413, 2019). "Recent reports suggested a tumor-suppressive role of H2Bub1 and the RNF20/RNF40 complex in different cancer entities." (PMID 37770435, 2023). "In this review, we summarize current knowledge about RNF40 gene structure and the role of RNF40 in histone H2B monoubiquitylation, DNA damage repair, apoptosis, cancer development, and metastasis." (PMID 33199825, 2021). "Further studies of RNF20 and RNF40 as potential targets for cancer therapy are warranted and urgently needed." (PMID 33199825, 2021). "We also underscore challenges in applying this information to cancer prognosis and prevention and highlight the urgent need for additional investigations of RNF40 as a potential target for cancer therapeutics." (PMID 33199825, 2021). "Through its protein ubiquitylation activity, RNF40 acts as a tumor suppressor or oncogene to play major epigenetic roles in cancer development, progression, and metastasis, highlighting the essential function of RNF40 and the importance of studying it." (PMID 33199825, 2021). "In this review, we summarize the current knowledge of RNF40 gene structure and function, focusing on its role in H2B monoubiquitylation, DNA damage repair, apoptosis, cancer development, and cancer metastasis." (PMID 33199825, 2021). "H2Bub1, RNF20 and/or RNF40 have been investigated in numerous cancer tissues, including breast, ovarian, colorectal, lung, gastric, kidney and parathyroid." (PMID 33233707, 2020). "Additionally, DDX27, MDM2, RNF40, MMS22L, CCNK and LRP1B were detected as missense mutational cancer gene." (PMID 34313788, 2021). "To date, only few studies examined RNF40 expression in cancer." (PMID 33070155, 2020). "RNF40 may predominantly act as a tumor suppresser through H2Bub1 modifications during carcinogenesis, but could also act as an oncogene through ubiquitylation of nonhistone proteins, such as Eg5, during metastasis or advanced stages of cancer." (PMID 33199825, 2021). "Moreover, synthetic lethal strategies have the unique benefit of enabling targeting of loss-of-function alterations, which would be relevant for cancer types frequently exhibiting reduced expression of E3 ubiquitin ligases (e.g., RNF20 or RNF40) or DUBs (e.g., BAP1 or USP22)." (PMID 30781493, 2019). "Together, these findings suggest that RNF40-mediated H2B monoubiquitination has a highly context-dependent function and may exert pro-tumorigenic functions in certain cellular contexts and thereby serve as a potential anti-cancer target." (PMID 31266541, 2019). "These tumor suppressor genes downregulated in cancer are PDCD4-AS1, RNF40, USP4, and ST13P5." (PMID 41347211, 2025). "Of note, parallel investigations of the group on HER2+-BC revealed that this RNF40-mediated mechanism was specific for TNBC cancer cells (data not shown)." (PMID 37770435, 2023). "On the other hand, DDX27, RNF40, MMS22L and CCNK have not been reported as mutational cancer genes in previous studies." (PMID 34313788, 2021).
cancer (continued). "Our data suggest that RNF40-driven H2B monoubiquitination plays a decisive, context-specific function in HER2+-BC by controlling the actin regulatory circuit and downstream signaling to maintain antiapoptotic signaling and promote cellular migration in cancer cells." (PMID 33070155, 2020). "Whether defective Rnf20 or Rnf40 leads to defective cohesion and CIN in human cells, and whether this contributes to tumorigenesis initiation and progression, is worth pursing in order to reveal the genetic basis of CIN in cancers." (PMID 29058668, 2017). "The PHKG2 and RNF40 genes are either overlapping or close to the sequences of SCAR marker BC13-4, while SCAR marker BC10-1 is in the intron and overlap the DPEP1 gene, suggesting that alterations in the expression of these genes could contribute to cancer progression." (PMID 28410206, 2017).
tumor (18 papers, 2016 to 2025). "Taken together, high RNF20 and RNF40 levels are associated with poor patient survival and play a tumor-supportive role in CC." (PMID 40597205, 2025). "In line with our previous findings, a gap closure assay and Boyden chamber assay revealed that the loss of RNF20 and RNF40 both impaired tumor cell migration." (PMID 40597205, 2025). "Furthermore, RNF40 loss strongly inhibited HCC1806 tumor growth in a chorioallantoic membrane (CAM) assay." (PMID 37770435, 2023). "Immunohistochemistry analyses have shown that RNF40 expression in tumor tissues is significantly higher than that in surrounding normal tissues and high levels of RNF40 are significantly associated with alpha-fetoprotein and tumor-node-metastasis tumor stage." (PMID 33199825, 2021). "However, both heterozygous (Rnf40wt/fl), and especially homozygous loss of Rnf40 (Rnf40fl/fl) resulted in a pronounced increase of tumor-free survival of MMTV-Erbb2 animals." (PMID 33070155, 2020). "To take possible reciprocal compensatory effects of the two E3 ligases into consideration, we combined RNF20 and RNF40 expression data (H2Bub1 score) better reflecting the activity of the H2Bub1 pathway in the tumor samples." (PMID 40597205, 2025). "Collectively, this study unveils a novel tumor-supportive role of RNF40 and underpins its high therapeutic value to combat the malignant behavior of TNBC." (PMID 37770435, 2023). "These subtle regulatory processes specifically affect genes that control genome stability and cell growth, supporting the inference that RNF20 and RNF40 act as tumor suppressors." (PMID 33199825, 2021). "Global levels of H2Bub1 and/or its E3 ligase complex members RNF20 and RNF40, have been investigated in numerous tumours using methods including immunohistochemistry and for RNF40 and/or RNF20, assessment of transcript levels and promoter hypermethylation." (PMID 33233707, 2020). "RNF40 has been reported to exhibit both tumor-suppressive and oncogenic roles in BC cells." (PMID 39895796, 2025). "Noteworthy, our group recently unraveled a strong tumor-supportive role of RNF40 repressing apoptosis by fostering the expression of important members of the actin cytoskeleton regulatory network and promoting focal adhesion kinase (FAK) activity in HER2+-BC in vitro and in vivo." (PMID 37770435, 2023). "Specifically, epithelial-specific deletion of Rnf40, either heterozygous or homozygous, in a mammary carcinoma mouse model increased their tumor-free survival and decreased the number of tumors they developed along with the kinetics of tumor growth." (PMID 35954248, 2022). "The role of RNF40 as a tumor repressor or oncogene will be presented here." (PMID 33199825, 2021). "Taken together, these studies suggest that RNF40’s role in tumor development is subtype specific." (PMID 33199825, 2021). "In this regard, RNF40 might exert both tumor-suppressor and oncogene functions, an issue that deserves to be further studied." (PMID 33199825, 2021). "Surprisingly, our previous work revealed that the H2B ubiquitin ligase RING finger protein 40 (RNF40) might exert tumor-promoting functions." (PMID 31266541, 2019). "Interestingly, we recently reported a tumor-supportive role of the RNF40/H2Bub1-axis in HER2+-BC, but such a connection was so far unknown in BLBC." (PMID 37770435, 2023). "Notably, several reports argue for a tumor-suppressive role of RNF40." (PMID 33199825, 2021). "The tumor suppressors PDCD4-AS1, RNF40, USP4, and ST13P5 are good candidates for knock-in experiments to see if an increase in expression causes less or more proliferation." (PMID 41347211, 2025). "While we and others have uncovered potential opposing tumor-supportive or tumor-suppressive roles of H2Bub1 and its E3 ligases RNF20 and RNF40 in ER-positive and triple-negative BC11,12,16, the role of this epigenetic pathway in HER2+-BC is currently unclear." (PMID 33070155, 2020).
tumor (continued). "In basal-like TNBCs, there is an inverse relationship between USP44 and RNF20/RNF40 with USP44 being more highly expressed, concomitant with lower levels of H2Bub1 in these tumours." (PMID 33233707, 2020). "Consistent with potential tumor suppressor functions of RNF20/40 and H2Bub1 and their requirement for stem cell differentiation, we observed a widening of H3K4me3 peaks on RNF40-dependent lineage-specific genes during adipocyte differentiation." (PMID 28209164, 2017). "Tumour growth in athymic mice receiving tumours with RNF20, RNF40, Eg5 knockdown or Eg5 inhibition, was significantly suppressed, arguing for a role of the RNF20/40-Eg5 axis in breast carcinogenesis." (PMID 27557628, 2016). "The results indicated that tumour growth was significantly suppressed in athymic mice which had received tumours with either RNF20, RNF40, Eg5 knockdown or monastrol treatment." (PMID 27557628, 2016). "Our work demonstrates a previously unknown tumor-supportive role of RNF20 and RNF40 by regulating the peroxisome functions and thereby suppressing ferroptosis." (PMID 40597205, 2025). "Since different tumor suppressors and oncogenes are controlled by the Ub- and proteosome-mediated degradation, the CSN7A, UBAC1, PSMD9, and RNF40 may play important roles in the pathogenesis of the KIRC." (PMID 36180558, 2022). "Unfortunately, due to the limited number of primary HER2+-BC samples analyzed in this study, we were not able to detect any correlation of H2Bub1 or RNF40 levels to tumor grade." (PMID 33070155, 2020). "Interestingly, a positive correlation of RNF20 but not RNF40 to Ki67 was observed in the tumor cell cluster of SCC, pointing at a potential oncogenic function of this RNF20 and RNF40 driven H2Bub1." (PMID 40597205, 2025). "Consistent with the lack of a complete block in tumor incidence and growth, Rnf40fl/fl lesions displayed a heterogeneous pattern of RNF40 expression, suggesting that the few tumors that did develop in this model were largely caused by an incomplete deletion of the Rnf40 allele." (PMID 33070155, 2020). "Together, our data do not support a general tumor-suppressive function of RNF40 and H2Bub1." (PMID 33070155, 2020). "In addition to H2B, nonhistone substrates of RNF20/40 have been reported, although it cannot be concluded whether RNF20 or RNF40 act through ubiquitylation of such nonhistone proteins to exert their tumor-suppressive or oncogenic functions." (PMID 33199825, 2021). "As suggested by the previous results, tumor tissues expressed higher levels of RNF20 and RNF40 than normal and surrounding tissues." (PMID 40597205, 2025). "Interestingly, the ability of HeLa and SiHa cells to form colonies under 2D conditions and tumor spheres under non-adherent 3D conditions was greatly reduced in the absence of RNF20 and RNF40." (PMID 40597205, 2025). "At present, it cannot be excluded that some tumour-suppressive or oncogenic functions of RNF20 and RNF40 might occur via non-histone substrates." (PMID 30669413, 2019).
inflammation (2 papers, 2021 to 2025). Aberrant reaction of the microcirculation characterized by movement of fluid and leukocytes from the blood into extravascular tissues. "Thus, the intestinal deletion of Rnf20 and Rnf40 in murine IECs is associated with gene expression profiles induced in murine and human intestinal inflammation." (PMID 34088983, 2021).
peripheral neuropathy (1 paper, 2020). A disorder affecting the peripheral nervous system. "Rnf40-deficient Schwann cells were arrested immediately before myelination or generated abnormally thin, unstable myelin, resulting in a peripheral neuropathy characterized by hypomyelination and progressive axonal degeneration." (PMID 32672815, 2020).
RNF40 also shares sentences with these, for which no sentence is quoted: hepatocellular carcinoma (2 papers); adenocarcinoma (1); autoimmune disease (1); bladder cancer (1); congenital heart disease (1); endocervical adenocarcinoma (1); infection (1); leukemia (1); lung adenocarcinoma (1).